HDGF (heparin binding growth factor)
Diseases named in the same sentence as HDGF in open-access papers (continued):
Sharing a sentence is not in itself a finding about the gene and the disease.
cancer (98 papers, 1997 to 2026). A tumor composed of atypical neoplastic, often pleomorphic cells that invade other tissues. "Midkine (MDK) is a heparin-binding growth factor implicated in the pathogenesis of various diseases, including cancer, chronic inflammation, and multidrug resistance (MDR)." (PMID 40500394, 2025). "Dysregulated overexpression of HDGF has been identified in multiple solid tumors and is associated with inferior clinic outcome of patients with cancer." (PMID 39041204, 2024). "HDGF has also been reported to be implicated in many cancer processes, including cancer growth, apoptosis, angiogenesis, and metastasis." (PMID 35351053, 2022). "A large amount of the evidence suggests that HDGF overexpression is associated with the aggressive phenotypes of cancer cells, such as proliferation, invasiveness, and metastasis." (PMID 30513684, 2018). "(iv) HDGF neutralizing antibody (HDGF-NAb) significantly inhibit HDGF-mediated expression of carcinoma-associated myofibroblast/fibroblast markers in HBMMSCs." (PMID 30513684, 2018). "Several findings suggest that HDGF overexpression is associated with aggressive phenotypes of cancer cells, such as proliferation, invasiveness, and metastasis." (PMID 24692842, 2014). "HDGF has been implicated in cancer cell proliferation and angiogenesis." (PMID 34106558, 2021). "HDGF overexpression has been implicated in the development of malignant tumors; however, the mechanism behind HDGF regulation is largely unknown." (PMID 30513684, 2018). "Furthermore, several recent experimental studies showed HDGF to be associated with the malignant phenotype of cancer cells." (PMID 26101867, 2015). "Since clinical studies showed that high HDGF expression levels were associated with a poor prognosis in several malignant diseases, we consider that the inhibition of HDGF could provide a new strategy for cancer therapy." (PMID 32545762, 2020). "A series of sulfated oligosaccharides (one tetra- and ten disaccharides) have been synthesized to study their interactions with midkine, a heparin-binding growth factor involved in cancer and inflammation." (PMID 41891761, 2026). "Midkine (MDK), a secreted heparin-binding growth factor, has recently emerged as a regulator of the cancer-immune interface." (PMID 42004035, 2026). "Our findings are consistent with HDGF’s role in activating growth and angiogenic pathways in other cancers." (PMID 41278276, 2025). "According to some reports, HDGF induces VEGF-dependent angiogenesis by activating HIF-1α in cancers." (PMID 40770862, 2025). "In this study, we found different signaling for cancer progression and invasion of human gastric organoids in response to recombinant HDGF and TNFα during the infection with H. pylori." (PMID 37047540, 2023). "It has been reported that HDGF upregulation by H. pylori infection can promote tissue damage and even cancer development by production of excess reactive oxygen species." (PMID 37047540, 2023). "Marsdenia tenacissima extract can disturb the cell–cell interaction between cancer cells and TAMs by regulating HDGF and increasing the polarization of macrophages from the M2 type to the M1 type." (PMID 38022518, 2023). "Here, we provide evidence of different signaling for cancer progression and invasion of human gastric organoids in response to HDGF and TNFα during infection by H. pylori." (PMID 37047540, 2023). "The hepatoma-derived growth factor (HDGF), which has mitogen activity and increased expression in a variety of cancers, has been identified as an additional target of miR-129-5p." (PMID 37111734, 2023). "HDGF controlled the growth of each organoid in a species-specific manner of H. pylori, but TNFα decreased the cell viability in H. pylori-infected cancer organoids." (PMID 37047540, 2023). "PTN is a heparin-binding growth factor, with potent mitogenic and angiogenic activity, and a crucial regulator of cancer metastasis, bone development, and bone repair." (PMID 37082621, 2023).
cancer (continued). "The human clinical data of ACC and STAG showed that HDGF and TNFα acted inversely to produce cancer phenotypes." (PMID 37047540, 2023). "Hepatoma-derived growth factor (HDGF) is a heparin-binding protein that has been discovered to present an aberrant expression in multiple cancers and partake in the modulation of malignant cancer cell behaviors like apoptosis, metastasis, and angiogenesis." (PMID 35014946, 2022). "Using a combined approach (proteomics, bioinformatics, and nanotechnology) they successfully enriched and identified hepatoma-derived growth factor (HDGF) in the corona of positively charged AuNPs after incubated with cancer cell lysates." (PMID 35887030, 2022). "We further analyzed HDGF since it exhibits mitogenic activity and is highly expressed in a variety of cancers." (PMID 35578240, 2022). "In contrast, it has been demonstrated that knockdown of HDGF gene induces apoptosis and cell cycle arrest in several human cancers." (PMID 34227049, 2022). "Mechanistically, the m5C methyltransferase NSUN2 and the m5C reader YBX1 drive cancer progression by targeting the m5C methylation site of the 3′ untranslated region of HDGF." (PMID 36532062, 2022). "HDGF plays a vital role in the transformation, apoptosis, angiogenesis, and metastasis of cancer cells." (PMID 36003381, 2022). "The upregulation of mRNA expression of several oncogenes, including FOSL2, TUFT1, HMGA1, and HDGF, most often leads to the acquisition of cisplatin resistance, while increasing the proliferation of cancer cells and reducing their apoptosis." (PMID 36139487, 2022). "To further deep into the mechanism mediating IFN-γ-triggered EMT activation, we focused on MDK, which is a heparin-binding growth factor and an emerging oncoprotein well implicated in induction of EMT and cancer metastasis." (PMID 35747815, 2022). "MKLN1-AS has been shown to serve as a molecular sponge for miR-654-3p, upregulate the expression of HCC-derived growth factor (HDGF), and promote cancer growth." (PMID 36159561, 2022). "Hepatoma-derived growth factor (HDGF) is a novel growth factor that is involved in numerous cancer processes, including cancer growth, apoptosis, angiogenesis, and metastasis." (PMID 35757505, 2022). "MDK is a heparin-binding growth factor and acts as a mediator for the acquisition of critical hallmarks of cancer, including cell growth, survival, metastasis, migration, and angiogenesis." (PMID 33828969, 2021). "HDGF is a critical regulator of cancer cell activities and plays central roles in transformation, apoptosis, angiogenesis and metastasis in several cancer types." (PMID 34094926, 2021). "For instance, NSUN2 targets the 3' untranslated region and stabilizes the mRNA of heparin binding growth factor, which regulates cancer progression." (PMID 34512153, 2021). "LEDGF/p75 is a member of the hepatoma-derived growth factor (HDGF) family, which includes HDGF, HRP2 (also known as HDGF2 or HDGFRP2), HRP3, and HDGFL1, and has been implicated in cancer cell proliferation and survival." (PMID 34685704, 2021). "As an important regulator of cancer, HDGF can be down-regulated through the EMT signaling pathway and the MMP-2 and MMP-9 signaling pathways." (PMID 34676171, 2021). "HDGF is a secreted growth factor, which can interact with the β-catenin pathway and promote cancer cell proliferation." (PMID 34676171, 2021). "The HDGF family of chromatin binding proteins, which in addition to DFS70/LEDGF also includes HDGF, HRP2/HDGF2 (HDGF-related protein 2), HRP-3, and HDGF-L1, has been implicated in promoting cancer cell proliferation and survival." (PMID 32127038, 2020). "HDGF participates in the progression of various digestive malignancies, and serves as an independent prognostic factor." (PMID 32545762, 2020). "Recently, some studies have demonstrated that HDGF serves an oncogenic function in many cancer types." (PMID 33290265, 2020).
cancer (continued). "Compared with adjacent nontumor liver tissues, there was a significant increase in nuclear HDGF (nHDGF) expression in cancer tissues." (PMID 30004626, 2018). "Midkine (MDK) is a heparin-binding growth factor prominently expressed in embryonic tissues but down-regulated to negligible levels in healthy tissues of adults, which is considered to be a “pan-cancer” biomarker." (PMID 30001734, 2018). "It is reported that HDGF is an important regulator of many cancer cell activities during transformation, apoptosis, angiogenesis, and metastasis." (PMID 30004626, 2018). "HDGF is a broad regulator of cancer cell activity and is involved in many cellular processes including transformation, apoptosis, angiogenesis, and metastasis." (PMID 30004626, 2018). "Whereas the cancer epithelial cell-enriched proteins were characterized of proliferation feature, such as hepatoma-derived growth factor (HDGF), bone morphogenetic protein 7 (BMP7) and tumor protein D52." (PMID 26338966, 2015). "A high HDGF expression is related to several unfavorable cancer characteristics, including rapid growth, significant invasiveness and metastasis, and it is also associated with poor prognoses of various malignant diseases." (PMID 26101867, 2015). "Hepatoma-derived growth factor (HDGF) is a unique nuclear/growth factor that plays an important role in the progression of different types of cancer." (PMID 25421244, 2014). "Differentially-expressed genes between radio-sensitive and -resistant cancer cells have been studied, and one in particular, Hepatoma-derived growth factor (HDGF) has been identified, whose expression is suppressed in radio-resistant cell lines." (PMID 25421244, 2014). "In fact, several reports have found a correlation between an increased HDGF expression and poor prognosis in various cancers." (PMID 25421244, 2014). "Midkine (MDK) is a heparin-binding growth factor that is highly expressed in many malignant tumors, including lung, esophageal, stomach, colon, hepatocellular, breast, renal and pancreatic carcinoma." (PMID 23976985, 2013). "HDGF is highly expressed in a wide variety of carcinomas and has been shown to be a valid prognostic marker." (PMID 23305559, 2013). "Midkine is a heparin-binding growth factor that is over-expressed in various human cancers and plays important roles in cell transformation, growth, survival, migration, and angiogenesis." (PMID 18275606, 2008). "The level of expression of midkine (MK), a heparin-binding growth factor, is increased in many types of human carcinomas." (PMID 10952771, 2000). "It has been suggested that a heparin-binding growth factor, midkine (MK), plays an important role incarcinogenesis because of its frequent overexpression in various malignant tumours." (PMID 10408712, 1999). "Midkine (MK) is a heparin-binding growth factor and is frequently expressed at high levels in many human carcinomas." (PMID 9020479, 1997). "YBX1 specifically targets severalm5C-containing oncogenes (e.g., Hepatoma-derived growth factor (HDGF)) andpromotes their stability and subsequent cancer progression by recruitingELAV-like RNA-binding protein 1 (ELAVL1), a well-known mRNA stability maintenancefactor." (PMID 41209125, 2025). "These cross-cancer evidences robustly validate the therapeutic value of targeting HDGF, laying a solid foundation for developing mono- or combination therapies involving anti-HDGF antibodies for the treatment of HSCC." (PMID 41278276, 2025). "HDGF may be a target for inhibiting the proliferation of cancer stem cells and preventing the recurrence of lung cancer after chemotherapy." (PMID 38725864, 2024). "Interestingly, HDGF was more commonly found to regulate Wnt/β-catenin pathway than autophagy in cancer cells 239-242." (PMID 38725864, 2024). "Stress or apoptosis of cells could increase the level of HDGF released into the media, a condition that is relevant to cancer therapy." (PMID 39041204, 2024).
cancer (continued). "Surprisingly, HDGF and TNFα decreased the cell viability of the cancer organoids." (PMID 37047540, 2023). "In all cases, the recombinant HDGF and TNFα were inhibitory to the growth of 3-D cancer organoids." (PMID 37047540, 2023). "Furthermore, HDGF controlled the invasion activity of H. pylori-infected cancer organoid in a species-dependent manner." (PMID 37047540, 2023). "Indeed, HDGF has been demonstrated to play important roles in various pathological processes, including cancer cell growth, transformation, apoptosis, and metastasis." (PMID 37827291, 2023). "Hepatoma-derived growth factor (HDGF) overexpression and uncontrolled reactive oxygen species (ROS) accumulation are involved in malignant transformation and poor prognosis in various types of cancer." (PMID 37827291, 2023). "Antibodies targeting HDGF could prevent NSCLC relapse after chemotherapy by suppressing cancer stem cells." (PMID 37301856, 2023). "HDGF overexpression has been reported in many types of cancers." (PMID 35351053, 2022). "HDGF regulates the proliferation, angiogenesis, and apoptosis of cancer cells; thus, one therapeutic option may be to use antagonists of exosomal lncRNA HEIH." (PMID 36139487, 2022). "After siRNA-mediated knockdown of HDGF, its cancer-related functions were examined." (PMID 35578240, 2022). "In addition, MKLN1-AS increases HDGF expression by functioning as a molecular sponge for miR-654-3p, resulting in a cancer-promoting effect during the HCC process." (PMID 34869306, 2021). "However, other studies have reported that an HDGF knockdown can induce apoptosis and cell cycle arrest in several human cancers." (PMID 33727914, 2021). "An increasing number of studies have shown that the overexpression of HDGF is correlated with unfavorable clinical outcomes in several malignant diseases, suggesting that HDGF could be a new molecular target for cancer therapy." (PMID 32545762, 2020). "Midkine (MDK) is a heparin-binding growth factor that is overexpressed in various types of human cancers, but its clinical significance is still unknown in CCA." (PMID 33193605, 2020). "Although identified as a growth factor, the mechanism by which hepatoma‐derived growth factor (HDGF) promotes cancer development remains unclear." (PMID 30004626, 2018). "Since the levels of lipogenic enzymes were associated with the PWWP domain of HDGF, we analyzed whether changes in the PWWP domain type affected lipid metabolism in cancer cells." (PMID 30004626, 2018). "Moreover, increasing investigations revealed that HDGF is significantly correlated with the malignant biological potential of a variety of cancer cells including PCa cells." (PMID 29300772, 2018). "The human hepatoma-derived growth factor (HDGF), containing the chromatin-associated N-terminal PWWP domain capable of binding the SMYD1 promoter, participates in various cellular processes and is involved in human cancers." (PMID 29321480, 2018). "Moreover, HDGF involves in the aggressive biological properties, including invasiveness, angiogenesis and metastasis of cancer cells." (PMID 29300772, 2018). "Pleiotrophin (PTN) is a heparin-binding growth factor which is overexpressed in many cancers." (PMID 26914549, 2016). "Midkine, a heparin-binding growth factor, has been identified as a promising cancer biomarker." (PMID 27974680, 2016). "However, further studies are required before any definitive conclusions can be made regarding the functional role of HDGF in apoptosis, although most recent reports support the anti-apoptotic function of HDGF in various types of cancer cells." (PMID 26101867, 2015). "Although the specific function of this protein is unknown, recent studies have suggested that HDGF plays a role in the regulation of cancer development." (PMID 25421244, 2014).
cancer (continued). "The observations that HDGF regulates multiple cellular processes such as cell growth, cell transformation, migration, invasion, and is a prognostic factor for multiple cancers implies its importance as a therapeutic target for treating multiple human cancers, including HCC." (PMID 20846397, 2010). "Besides, HDGF participates in other cellular processes, such as renal development, cardiovascular differentiation, angiogenesis and sensitization of cancer cells to irradiation." (PMID 20846397, 2010). "Midkine (MDK) is a heparin-binding growth factor with multiple functions, including anti-apoptotic, migratory ion-promoting, angiogenic, and antimicrobial effects and is strongly expressed during embryogenesis and most malignant tumors, but in normal adult tissues, it is weak or undetectable." (PMID 32923383, 2020). "Studies that examine human cancers for the presence of these and other PWWP mutations would be worthwhile, as the PWWP binding motif is highly conserved in human hepatoma-derived growth factor (HDGF) which is overexpressed in a number of human cancers and is involved in PI3K signaling." (PMID 32477926, 2020). "Therefore, we hypothesized that the HDGF expression in human malignant tumors may also have an important functional role in metastasis and may consequently influence the prognosis of patients." (PMID 25421244, 2014). "Overexpression of miR-195-5p abated the cancer-promoting function of TUG1 and curbed the profile of the HDGF/DDX5/β-catenin axis." (PMID 35014946, 2022). "The heparin-binding growth factor MDK is a versatile oncoprotein well-reported in conferring cell proliferative and metastatic advantages in various cancers." (PMID 36672515, 2022). "Next, using cell line models, we found that the simultaneous suppression of HDGF and LGR5 synergistically disrupted the formation of cancer spheroids and downregulated the level of cancer stem cell markers." (PMID 34106558, 2021). "The HDGF cDNA plasmid was transfected to NAP1L1-suppressing cells, to explore the role of HDGF in NAP1L1-mediated pathogenesis of HCC cancer." (PMID 34368121, 2021). "Hepatoma-derived growth factor (HDGF) is commonly over-expressed and plays critical roles in the development and progression in a variety of cancers." (PMID 29300772, 2018). "Therefore, HDGF may prove useful as a prognostic factor for patients with cancers." (PMID 24692842, 2014). "Our study also revealed a novel function of HDGF in HCC, that is, to promote the cell migration and invasion, suggesting its potential involvement in cancer metastasis." (PMID 20846397, 2010). "MDK is a heparin-binding growth factor and has been reported to promote EMT in cancer cells." (PMID 38416732, 2024). "AS a heparin-binding growth factor, MDK is abnormally high expressed in a variety of human malignancies and serves as an intermediary agent for the acquiring critical features of cancer, such as proliferation, metastasis, chemoresistance, migration, and angiogenesis 35-38." (PMID 36594100, 2023). "miR-1252-5p is a miRNA that has not been studied until recent years, and hepatoma-derived growth factor (HDGF) is a novel jack-of-all-trades in cancer including NSCLC." (PMID 36694627, 2023). "MDK is a heparin-binding growth factor well-documented to promote EMT and cancer metastasis." (PMID 35747815, 2022). "Furthermore, another study demonstrated that HDGF directly binds to the promoters of GLUT4 and ENO2, thus inducing their expression in cancer and enhancing the Warburg effect." (PMID 35757505, 2022). "HDGF knockdown not only induces expression and de-phosphorylation of the pro-apoptotic protein Bad, but also inactivates ERK and Akt, resulting in activation of the intrinsic apoptotic pathway in cancers." (PMID 34227049, 2022). "The elevated expression of HDGF is related to many types of cancer, which, irrespective of cancer type, correlates with a poor prognosis." (PMID 31162607, 2019).